CGA (glycoprotein hormones, alpha polypeptide)
Diseases named in the same sentence as CGA in open-access papers (continued):
Sharing a sentence is not in itself a finding about the gene and the disease.
prostate adenocarcinoma (8 papers, 2004 to 2025). "The expression of CgA or other neuroendocrine markers is often observed in prostate adenocarcinomas, particularly after exposure to ADTs." (PMID 37240468, 2023). "As established, NEPC was distinguished from prostate adenocarcinoma based on NE markers (NSE, CgA, Syn, CD56) and the loss of PSA expression." (PMID 36118857, 2022). "Our main objective was to identify the correlation between AR status and CgA level before the administration of anti-AR therapies and in different settings (chemotherapy-naïve and chemotherapy-treated patients) in prostate adenocarcinoma." (PMID 30337589, 2018). "In addition, increased CgA concentrations are encountered in gastric and pancreatic cancer, prostate adenocarcinoma, and colorectal and hepatocellular cancer." (PMID 40455177, 2025). "Genome wide DNA sequencing could also be used to study other molecular mechanisms that may lead to the progression of CRPC to NEPC, an effort to define a molecular phenotype of mixed forms between prostate adenocarcinoma and NEPC in association with CgA levels." (PMID 30337589, 2018). "The tumor presenting the highest NTR1 expression was a poorly differentiated prostatic adenocarcinoma (CK20−, CK7−, PSAp+, p63−, p504s+) without neuroendocrine differentiation (CgA-, synaptophysin-), Gleason 9, node-positive, T3, R0." (PMID 30959962, 2019). "NK1R was highly expressed in NE-like cell lines PC-3 and DU145, both positive of NE markers (CgA and ENO2) and negative of AR/PSA; in contrast, in AR-positive prostate adenocarcinoma cell line LNCaP and 22Rv1, NK1R expression is much lower and NE markers are marginal." (PMID 37385990, 2023).
Anxiety (7 papers, 2008 to 2025). Intense feelings of nervousness, tension, or panic often arise in response to interpersonal stresses. "Anxieties over public speaking, academic exams, performance anxiety, and other emotionally taxing situations have all been linked to elevated salivary CgA levels." (PMID 40728957, 2025). "Fifth, only age, gender, and BMI were adjusted in the multiple linear regression model for the associations of anxiety/depression with CgA/catestatin." (PMID 32515855, 2020). "Our study was to investigate the associations between anxiety/depression and plasma CgA/catestatin levels." (PMID 32515855, 2020). "In summary, we found that anxiety/depression was positively associated with plasma CgA, while anxiety was negatively associated with catestatin levels in healthy workers." (PMID 32515855, 2020). "In the study of the associations between anxiety/depression and CgA, most studies have confirmed the correlation between anxiety/depression and the level of CgA." (PMID 32515855, 2020). "Plasma CgA was associated with anxiety and depression in healthy workers." (PMID 32515855, 2020). "Fourth, needle insertion may cause pain, anxiety, and stress during blood sample collection, so we need to consider whether this reaction will affect the levels of CgA and catestatin." (PMID 32515855, 2020). "Anxiety/depression was independently associated with plasma CgA level." (PMID 32515855, 2020). "The following are promising salivary biomarkers of stress, anxiety or depression: cortisol, immunoglobulin A (sIgA), lysozyme, melatonin, α-amylase (sAA), chromogranin A (CgA) and fibroblast growth factor 2 (FGF-2)." (PMID 33535653, 2021). "It supports that plasma CgA can be considered as an objective index for the evaluation of anxiety and depression." (PMID 32515855, 2020). "Therefore, the associations between plasma CgA level and anxiety/depression are unknown." (PMID 32515855, 2020). "In our study, we found that plasma CgA levels have increased significantly in healthy individuals with anxiety or depression." (PMID 32515855, 2020). "Therefore, the association between depression and plasma CgA level may be caused by anxiety." (PMID 32515855, 2020). "Hence, the objective measurement of the salivary CgA concentration also supported the effect of REP hydrolysate in the reduction in subjective feelings of anxiety and nervousness." (PMID 37571427, 2023). "Many studies have shown that plasma CgA and catestatin levels play important roles in cardiovascular diseases, so we speculated that anxiety/depression might play roles in cardiovascular diseases by changing plasma CgA and catestatin levels." (PMID 32515855, 2020). "The study was to investigate the associations between anxiety/depression and plasma CgA/catestatin levels in healthy workers without cardiovascular disease." (PMID 32515855, 2020). "Many studies have confirmed the correlation between anxiety/depression and the salivary CgA level." (PMID 32515855, 2020). "In this study, the plasma CgA level was higher in patients with anxiety or depression." (PMID 32515855, 2020). "In our study, plasma CgA level was significantly correlated with anxiety and depression." (PMID 32515855, 2020). "The plasma CgA could be considered as the blood indicator for the evaluation of anxiety and depression." (PMID 32515855, 2020). "The aim of our study was to investigate the associations between anxiety/depression and plasma CgA/catestatin levels in healthy workers without cardiovascular disease." (PMID 32515855, 2020). "We hypothesized that abdominal muscle stretching as a passive operation would have a beneficial effect on a biochemical index of the activity of the sympathetic/adrenomedullary system (salivary CgA) and anxiety." (PMID 18983682, 2008).
Anxiety (continued). "Changes in the Gastrointestinal Symptoms Rating Scale (GSRS), State Trait Anxiety Inventory (STAI), Self-rating Depression Scale (SDS), ordinate scale and salivary CgA levels were compared between controls and IBS subjects before and after stretching." (PMID 18983682, 2008). "Most of these studies have confirmed a correlation between salivary CgA level and anxiety or depression, while a few did not." (PMID 32515855, 2020). "Regardless of the presence or absence of depression, anxiety was correlated with plasma CgA and catestatin levels, while depression was no longer correlated with plasma CgA level after adjusting for anxiety." (PMID 32515855, 2020). "The anxiety group had significantly higher plasma CgA level than that in the no‐anxiety group (median 158.60 vs 70.90, P < .001)." (PMID 32515855, 2020). "Also during re-uniting episodes, dogs and owners spent more time near each other when owner CgA levels were low, owner CORT levels were high, and the dog had owner-reported separation anxiety." (PMID 31396061, 2019). "The single intake of REP hydrolysate did not improve the Euthymia Scale or all of the subscales of POMS 2; yet, it showed a significant improvement in the POMS 2 Tension–Anxiety score and a significant reduction in the salivary CgA concentration without adverse effects." (PMID 37571427, 2023).
gastroenteropancreatic neuroendocrine neoplasms (7 papers, 2006 to 2023). "Chromogranin A (CgA) is a well-established marker for diagnosis and follow up of patients with gastroenteropancreatic neuroendocrine neoplasms (GEP-NEN)." (PMID 29232390, 2017). "Chromogranin A (CgA) not only plays an important role in pathologic diagnosis, but is also used as a circulating biomarker in patients with gastroenteropancreatic neuroendocrine neoplasm (GEP-NEN)." (PMID 25501094, 2014). "CgA expression was probably higher in pancreatic neuroendocrine neoplasms than in gastrointestinal neuroendocrine neoplasms (P = 0.05)." (PMID 25501094, 2014). "A study suggested that SRS is more sensitive, more specific, and more accurate than chromogranin A (CgA) levels (a recognized marker for carcinoid tumours) for metastatic evaluation of carcinoid tumours." (PMID 23997766, 2013). "Two markers are primarily used to diagnose and follow carcinoid tumours: 5-hydroxy-indole-acetic acid (5-hiaa) and chromogranin A (CgA)." (PMID 17576444, 2006). "However, we found that CgA expression was probably lower in gastrointestinal neuroendocrine neoplasms than in pancreatic neuroendocrine neoplasms." (PMID 25501094, 2014). "In gastroenteropancreatic neuroendocrine neoplasms (GEP-NENs), histological examination reveals a trabecular or solid arrangement and immunohistochemical analysis reveals the expression of neuroendocrine markers (Syn and CgA)." (PMID 25780425, 2015). "In general, CgA levels are elevated in 85%–100% of patients with carcinoid tumour, regardless of whether the tumour is functional or nonfunctional." (PMID 17576444, 2006).
carcinoid syndrome (6 papers, 2012 to 2024). "More specifically for SI-NETs CgA should be used and interpreted with caution, given that diagnostic accuracy is limited, while 5HIAA should be followed especially for surveillance of carcinoid syndrome." (PMID 34681049, 2021). "The highest CgA concentration in NENs is observed in carcinoid syndrome and in patients with liver metastases." (PMID 39451760, 2024). "Similarly, in the subgroup of patients with carcinoid syndrome, only Tie-2 and CgA concentrations were higher than those in patients with non-functioning NETs." (PMID 22408401, 2012). "Levels of CgA were found to be significantly higher in patients with carcinoid syndrome (298.8 ng/mL; range: 52.0–913.4 ng/mL) than in patients without carcinoid syndrome (82.9 ng/mL; range: 21.7–2795.1 ng/mL; P = 0.011)." (PMID 27159453, 2016).
hepatocellular carcinoma (6 papers, 2019 to 2025). A malignant tumor that arises from hepatocytes. "For example, it has been shown that CgA is also elevated in chronic liver diseases such as cirrhosis, hepatitis and hepatocellular carcinoma." (PMID 37770647, 2024). "Increased CgA levels have been detected in pancreatic adenocarcinoma and hepatocellular cancer as well: However, little is known concerning the potential pathophysiological meaning of the increase in CgA levels." (PMID 31382663, 2019). "CgA level can also be elevated in other non-NET cancers, such as breast cancer, thyroid cancer, pancreatic cancer, hepatocellular carcinoma, gastric cancer, colon cancer, and prostate cancer." (PMID 34868938, 2021).
insulinomas (6 papers, 2014 to 2023). "The mechanisms underlying low serum levels of CgA in insulinomas would appear to warrant further investigation." (PMID 25099181, 2014). "In the present study, we verified the diagnostic value of serum CgA in a series of patients with non-insulinoma PNETs, in agreement with previous studies." (PMID 25099181, 2014). "This study was to assess the diagnostic value of CgA in Chinese patients with PNETs especially in patients with insulinomas." (PMID 25099181, 2014). "Our data and previous reports showed that insulinoma could be an exception for measuring serum levels of CgA for diagnostic purpose." (PMID 25099181, 2014). "Thus, the present study is to verify the utility of CgA in diagnosis of PNETs, focusing on its diagnostic value in insulinoma." (PMID 25099181, 2014). "In the normal pancreatic islets, β-cells were lesser immunostained for CgA than other three non-β-cells and insulinomas were relatively weaker immunostained for CgA than non-β-cell tumors but as strongly stained for SPY as in non-β-cell tumors (Cases 7 and 9)." (PMID 32020844, 2020). "In the endocrine pancreas, β-islet cells are weaker immunostained for CgA than non-β cells, including α-, δ- and PP cells, which are densely immunostained for CgA, and insulinomas show mostly lesser CgA immunostaining than non-β-cell tumors." (PMID 32020844, 2020). "In our 13 cases of primary insulinomas, 10 cases (Cases 1,2,3,4,5,6,8,9,10 and 13) were much weaker immunostained for CgA as reflecting the immunostaining nature of β-cell-derived tumors." (PMID 32020844, 2020). "The serum CgA levels are higher in subjects harboring non-β-cell tumors than those harboring insulinomas, and the serum CgA elevates in parallel to the increasing metastatic tumor mass." (PMID 32020844, 2020). "Compared with the serum levels of CgA in the healthy controls, the CgA levels were significantly elevated in 32 patients with non-insulinoma PNETs (P = 3.7 × 10−7)." (PMID 25099181, 2014). "Our data above showed that CgA levels in patients with tumor metastases were significantly higher than that in patients with localized tumors and only 1 patient with metastasic insulinoma was included in our study." (PMID 25099181, 2014). "We correlated the CgA levels with clinicopathological features in patients with PNETs as well as insulinomas, respectively." (PMID 25099181, 2014). "In this study, we have observed that most of insulinoma tissues (12/14) were shown strong positive staining for CgA, indicating that insulinoma cells were able to synthesize the CgA protein." (PMID 25099181, 2014). "We compared serum CgA levels in 56 localized insulinoma with the CgA levels in 12 patients with localized non-insulinomas." (PMID 25099181, 2014). "We observed strong or medium expression of CgA in 12 of 14 insulinomas as well as in 11 of 12 non-insulinoma PNETs, as detected by IHC." (PMID 25099181, 2014). "Other than the low blood levels of CgA in insulinomas, the biomedical behaviors of insulinomas were quite different from other PNETs." (PMID 25099181, 2014). "We found CgA levels in localized insulinomas were similar to that in localized non-insulinomas, P = 0.693." (PMID 25099181, 2014). "The ROC curve showed that CgA cut-off values was 60.4 ng/ml for insulinomas and 73.9 ng/ml for non-insulinomas, respectively." (PMID 25099181, 2014). "In contrast, CgA values at 73.9 ng/ml distinguished patients with non-insulinoma PNETs from healthy controls, with a sensitivity and specificity were 65.6% and 91.9%, respectively, AUC was 0.805." (PMID 25099181, 2014). "It was reported that pancreastatin, a CgA-derived peptide (CgA residues 250–301) with biological activity, inhibited the releasing of insulin by islet beta cells and insulinoma cell line." (PMID 25099181, 2014). "In contrast, CgA values at 74 ng/ml distinguished patients with non-insulinoma PNETs from healthy controls, and the sensitivity and specificity were 65.6% and 91.9%, respectively." (PMID 25099181, 2014).
insulinomas (continued). "In present study, we focused on insulinomas and our findings were very similar to their data which showed only a small part of patients with insulinomas (7/57, 12%) had a slightly increased level of CgA (>100 ng/ml, the highest level: 164 ng/ml)." (PMID 25099181, 2014). "ROC curve showed that CgA values at 60 ng/ml distinguished patients with insulinomas from healthy controls but its sensitivity and specificity were 66.7% and 73.3%, respectively." (PMID 25099181, 2014). "Expression of CgA protein was detected in 26 PNET tissues including 14 insulinomas by immunohistochemical staining." (PMID 25099181, 2014). "The stronger staining of SPY than CgA in insulinomas may also implicate robust SPY participation in insulin secretion through endocytosis." (PMID 32020844, 2020). "In insulinomas, which contain less CgA than the other non-β-cell tumors, serum CgA levels are not increased in the patients but measurement of serum CgA is a helpful indicator for tumor metastasis by the increasing CgA-secreting tumor mass." (PMID 32020844, 2020). "CgA immunostaining is less in insulinomas than in non-β-cell tumors, and CgA immunostaining may distinguish CgA-weaker insulinomas from CgA-stronger non-β-cell tumors." (PMID 32020844, 2020). "The study revealed that the circulating CgA levels in patients with insulinomas were not obviously elevated, although we did validate the diagnostic value of serum CgA in a series of patients with non-insulinoma PNETs." (PMID 25099181, 2014). "We speculate that high levels of insulin in patients with insulinomas might inhibit the secretion of CgA in these tumor cells." (PMID 25099181, 2014). "Serum levels of CgA in 57 patients with insulinomas (median 64.8 ng/ml, range 25–164) were slightly higher than the levels in healthy controls (median 53.4 ng/ml, range 39–94) but much lower than the levels in 32 patients with non-insulinoma PNETs (median 193 ng/ml, range 27–9021), P = 0.001." (PMID 25099181, 2014). "Nevertheless, more patients with metastatic insulinomas were needed to validate the low levels of CgA in insulinomas although it might be quite difficult to do so due to the limited numbers of malignant insulinomas." (PMID 25099181, 2014). "Furthermore, we correlated the CgA levels with clinicopathological features in patients with insulinomas." (PMID 25099181, 2014). "However, we noticed that the rate of elevated CgA levels in patients with localized non-insulinomas was significantly higher than that in patients with localized insulinomas, P = 0.015." (PMID 25099181, 2014). "The median values of CgA levels in 86 healthy controls, 57 patients with insulinomas and 32 patients with non-insulinoma PNETs were 53.4 ng/ml (range 39.1 – 94.1 ng/ml), 64.8 ng/ml (range 25.0 – 164.2 ng/ml) and 192.5 ng/ml (range 26.9 – 9020.7 ng/ml), respectively." (PMID 25099181, 2014). "The serum CgA levels were reduced in 16 of 17 patients with insulinomas after tumor resection." (PMID 25099181, 2014). "In our cases, those with moderate CgA immunostaining (>++) in mixed more solid and less trabecular or lobular pattern may be considered as potentially malignant, which are more common in non-β-cell tumors than in insulinomas." (PMID 32020844, 2020). "CgA has been shown to be a reliable serum diagnostic biomarker for panNETs but not for insulinomas." (PMID 32183367, 2020). "Thus, CgA immunostaining may distinguish CgA-weaker insulinomas from CgA-stronger non-β-cell Pan-NETs." (PMID 32020844, 2020). "Thus, CgA immunostaining intensity may distinguish CgA-weaker, mostly benign insulinomas from CgA-stronger, more aggressive non-β-cell tumors." (PMID 32020844, 2020). "The underlying mechanism of low CgA levels in patients with insulinomas is not clear." (PMID 25099181, 2014). "Thus, it may hypothesized that few metastases in insulinomas would be the reason for low serum level of CgA in insulinomas (only one metastatic insulinoma in our serial)." (PMID 25099181, 2014).